EGFR (epidermal growth factor receptor)
Diseases named in the same sentence as EGFR in open-access papers (continued):
Sharing a sentence is not in itself a finding about the gene and the disease.
tumor (continued). "EGFR-FITC-SiO2-NPs and FITC-SiO2-NPs were administered into a blood vessel and after 24 h the CAM with tumor and the liver were removed for microscopic analysis." (PMID 31561451, 2019). "The TCGA CIN subtype was also notable for frequent EGFR amplification, including Erbb2 (HER2) (24% in CIN tumours in the TCGA cohort), and, accordingly, HER2 overexpression was seen exclusively in our CIN tumours (8/48, 16.7%)." (PMID 31790410, 2019). "Four proteins were found differentially expressed in KRAS-mutant as compared to wild-type tumours (overexpressed in mutant: KRAS, EGFR; overexpressed in wild-type: TOPO1, TOP2A)." (PMID 31537838, 2019). "MiR-141 functions as a tumor suppressor in HNSCC and that it suppresses tumor growth and metastasis by suppressing EGFR signaling." (PMID 30737360, 2019). "In tumour tissues, the positive areas for NM IIA were increased, while the positive areas for p‐CREB, EGFR and HK II were reduced." (PMID 31397978, 2019). "NEDD4, also known as neural precursor cell expressed developmentally downregulated protein 4, has been reported as E3 ligase for many substrates, including EGFR, PTEN, and ERBB4, and it was involved in tumor and other diseases." (PMID 31831018, 2019). "In vivo experiments have shown that inhibitors of EGFR, Ras, PI3K and Akt result in marked ‘normalisation’ of tumour microvasculature with durable increases in perfusion and alleviation of tumour hypoxia." (PMID 30991262, 2019). "The fact that multiple injections of DTEGF13 were tolerated in the animals is important because human EGF and IL-13 are cross-reactive with mouse EGFR and IL-13R, thereby showing a higher specificity of DTEGF13 for tumor cells and lower safety concerns." (PMID 31681205, 2019). "Receptor tyrosine kinases (RTKs), epidermal growth factor receptor (EGFR) and vascular endothelial growth factor receptor-2 (VEGFR-2) play vital roles in regulating tumor cell proliferation, differentiation, survival, angiogenesis and apoptosis." (PMID 30678347, 2019). "In agreement with previous work, we demonstrated for three targets (CD20, EGFR, and HER2) that the IgA isotype is very potent at triggering tumor cell killing by unstimulated neutrophils." (PMID 31031746, 2019). "Finally, EGFR signaling could be prolonged and exert influence on tumor progression." (PMID 30940109, 2019). "We also demonstrated that dual inhibition of EGFR and CXCR7 suppressed tumor cell growth and reduced MAPK activity by downregulation of pERK levels." (PMID 30935067, 2019). "In CRC, the main molecular markers available for active targeting are the carcinoembrionic antigen (CEA), the folate receptor alpha (FRα), and the epidermal growth factor receptor (EGFR and HER2) present onto the tumor cells." (PMID 31662751, 2019). "HGF, MET-amplification, and EGFR-T790M upregulate PD-L1 expression in NSCLC and promote the immune escape of tumor cells through different mechanisms." (PMID 31747941, 2019). "The expression of COX-2 and the sequential production of prostaglandin E2 are capable of up-regulating phosphoinositide-3-kinase (PI3K), EGFR and ERK1/2 signaling to trigger cell proliferation, angiogenesis, metastasis and invasion of tumor cells." (PMID 31123430, 2019). "In another study in C6 cells, P2X7 receptor suppression via use of antagonist or shRNA, promoted epidermal growth factor receptor (EGFR) signaling and growth of cells in in vitro, and tumor growth and angiogenesis in rat-transplanted in vivo models." (PMID 30691160, 2019). "These modules include the interaction between EGFRs and their ligands, the intracellular regulation of individual cells via the EGFR/ERK pathway, and the 3D multicellular biomechanics of early-stage tumour growth." (PMID 31016574, 2019). "A subset of drugs, including afatinib, dacomitinib, neratinib (EGFR), AZD2014 (mTOR), panobinostat (HDAC), and trametinib (MEK), showed exceptionally high anti-tumor activities across all gynecologic tumors." (PMID 31771620, 2019).
tumor (continued). "For instance, FOXP1 induction by inhibition of miR-9 promoted tumor growth, while FOXP1 knockdown suppressed the growth of epidermal growth factor receptor (EGFR) dependent cancers." (PMID 31815635, 2019). "In 3LL-D122-metastasis, of mice treated with the best combination, both EGFR and uPAR/α5β1 integrin pathways are turn off (I.e expression of uPAR/α5β1; and phosphorylation of EGFR, Stat3, Src and FAK are reduced); and tumor angiogenesis is decreased." (PMID 29844873, 2018). "The specificity of UniPR1331 for the Eph-ephrin system was evaluated by testing the compound on several targets promoting tumor angiogenesis (ICAM-1, PDGFR, and FGFR) and proliferation (TGF-β, EGFR)." (PMID 29849945, 2018). "It has been demonstrated that exposure to acute UV irradiation or treatment with the tumor promoter TPA increases the activation of protein tyrosine kinases, including the epidermal growth factor receptor (EGFR) and the downstream STAT3 signaling pathway." (PMID 29955047, 2018). "Following this first evidence, a proof-of-concept study in the subgroup of HER2-amplified xeno-patients demonstrated a significant tumor regression after combined treatment with HER2 and EGFR blockade." (PMID 34532592, 2018). "These EGFR-contained TEX activate MAPK and Akt/protein kinase B pathways in recipient ECs resulting in VEGF overexpression and increased tumor vascularity." (PMID 29720982, 2018). "In multivariable analysis including age, sex, tumor histology, tumor stage, performance status, EGFR and KRAS status, EGFR wild-type (sub-distribution hazard ratio 1.81, 95% confidence interval 1.07–3.07) were associated with the increased risk of VTE." (PMID 29743116, 2018). "More precise and effective treatment of patients with EGFR mutant NSCLC requires an in-depth understanding of the mechanisms of primary and recurring tumor-acquired resistance to EGFR-TKIs." (PMID 29691367, 2018). "Double transgenic mice (H2‐c‐fosLTR/ColAREG) showed significantly increased tumor numbers, size and a tendency of elevated serum ALP levels, indicating that autocrine osteoblast‐specific EGFR activation accelerates OS development." (PMID 30361264, 2018). "To verify the presence of anti–EGFR-GNs, which selectively target MDA-MB-231 cells, we performed silver staining in axillary LNs of tumor-bearing mice." (PMID 29484119, 2018). "For example, at cut of values of above 5% of tumour cells with positive staining, dual expression of EGFR/HER-2, EGFR/HER-3 and EGFR/HER-4 were present at 62%, 45%, and 28% of the cases examined respectively." (PMID 29731973, 2018). "c-MET has a tumor-promoting role in CRC and has been characterized as a resistance mechanism to EGFR-targeted therapy." (PMID 29455662, 2018). "Afatinib inhibited tumor growth in the PDX models with EGFR amplification, EGFR overexpression, or HER2 amplification." (PMID 29433585, 2018). "Of the three tumors with HER3 amplification, one tumor presented with normal EGFR, HER2 and HER3 CN, one tumor had normal EGFR and HER3 CN and HER2 low gain, while one of the three HER3 amplified tumors was non-informative regarding CN status." (PMID 30521571, 2018). "Potentially FCGR3B CNV can be used as a new biomarker for cancer immunotherapy, where patients can be stratified with likelihood of benefitting from therapy when patients have a lower FCGR3B CNV combined with the right tumor antigens (e.g., HER2/Neu or EGFR)." (PMID 30761158, 2018). "EGFR overexpression and amplification was frequently observed in ESCC and correlated with advanced tumor stage and poor prognosis." (PMID 29455652, 2018). "There are about 36.6% to 97% EGFR overexpression of ESCC patients, which is proved to correlate with lymph node metastasis, overall survival and pathologic tumor stages." (PMID 30131072, 2018).
tumor (continued). "A second biopsy was gathered from a mCRC patient whose tumour carried genetic alterations in RNF43 and BRAF genes, and clinically responded and then relapsed to EGFR blockade with cetuximab in combination with the BRAF inhibitor encorafenib." (PMID 29895949, 2018). "We demonstrate that the combination of EGFR-TKI and a β-catenin inhibitor inhibits the development of these adaptive persisters, decreases tumor burden, improves recurrence free survival, and overall survival in xenograft models." (PMID 30097569, 2018). "Several studies have shown that EGFR is expressed in bone and soft tissue tumors and that its expression is positively correlated with TNM (tumor-node-metastasis) stage in OS." (PMID 29751634, 2018). "JNJ-61186372: The anti-tumor activity of JNJ-61186372, a c-Met and EGFR bispecific antibody, was investigated in in vitro and in vivo studies involving NSCLC tumor models, and showed strong ability to reduce tumor growth." (PMID 30134579, 2018). "The tyrosine phosphorylation of epidermal growth factor receptor (EGFR) was inhibited upon Ley was downregulated, which leads to the reduction of cell proliferation and tumor growth." (PMID 30619732, 2018). "In our study, we evaluated the relationship of tumour perfusion and [18F]FLT tracer uptake responses in patients suffering from adenocarcinoma and treated with EGFR TKIs." (PMID 29594931, 2018). "When combined with these EGFR-targeting agents, COTI-2 was more effective at inhibiting tumor cell proliferation." (PMID 29364966, 2018). "In this regard, our results elucidated a new pathway of the EGFR signaling and suggested the potential therapeutic target of LOX for the treatment in tumor metastasis." (PMID 29472856, 2018). "We described here a novel low affinity anti-EGFR ADC, RN765C, designed to have potent anti-tumor activity in tumors with medium to high EGFR expression." (PMID 30323890, 2018). "Levels of EGFR and MSI1 mRNA expression were higher in tumor stage I/II in comparison with stage III/IV, whereas the levels of MSI1 expression were higher than the EGFR expression in patients with tumor stage I/II (1.66 ± 0.45 vs. 1.41 ± 0.52, fold changes)." (PMID 30202417, 2018). "Moreover, to observe the effect of tumor ratio, we performed macrodissection to enrich for tumor tissue, and then re-analyzed EGFR mutations in eight samples for which the cobas EGFR test had yielded negative results but the ddEGFR test yielded positive results." (PMID 29323170, 2018). "These complex regulations result in the high expression of both CCAT1 and EGFR, promoting SCC tumor progression through activating downstream MEK/ERK1/2 and PI3K/AKT signalings." (PMID 30190462, 2018). "Despite the high number of EGFR and HER3 present as verified through Bmax values, flow cytometry and immunoblots, the tumor accumulation of the probe in AsPC-1 xenografts uptake was lower compared to BxPC-3 models." (PMID 29899472, 2018). "EGFR and the mutant EGFRvIII are major focal points in current concepts of targeted cancer therapy for GBM, so they are considered to be responsible for tumor initiation, propagation, recurrence, and chemo- and radio-resistance." (PMID 30016965, 2018). "An alternative strategy is to develop dual-inhibitors targeting both EGFR/IGFR and VEGFR2 to increase their specificity for tumor EC-like cells." (PMID 30050899, 2018). "MUC1 is a tumor antigen that can modulate EGFR activity, with EGF-dependent degradation of EGFR inhibited by co-expression of MUC1." (PMID 29464085, 2018). "Particularly, we were able to detect unique activation of EGFR and IGF1R in CAF cells due to the communication with tumor cells." (PMID 29946230, 2018). "Based on our aggregated results, we propose a working model that disruption of ETV6 contributes to tumor progression and TKI-resistance through derepression of TWIST1 and activation of EGFR-RAS signaling." (PMID 29455655, 2018).
tumor (continued). "Of particular interest are peptide ligands for over-expressed receptors on tumor cells, such as the vascular endothelial growth factor receptor (VEGFR), somatostatin receptors and the epidermal growth factor receptor (EGFR and EGFRVIII)." (PMID 29914561, 2018). "Our studies focus on the views that FBXW7 executes its tumor suppressor function by inhibition of EMT and the mTOR/p70S6K pathway, ensuring the efficiency of EGFR‐TKI treatment in NSCLC." (PMID 29633504, 2018). "The low membrane EGFR concentrations on GSCs is concerning, given reports that EGFR signaling is necessary for GSC proliferation and tumor-sphere formation." (PMID 30050899, 2018). "However, the lack of on-chip identification of EGFR expression and corresponding sorting of EGFR-expressed cells compromises the feasibility of selectively sequencing EGFR-expressed cells which possibly make up a small portion of all cells extracted from tumor tissue." (PMID 30393665, 2018). "It was observed that co-administration of EGFR inhibitors with apatinib, a highly selective VEGFR2 inhibitor reduced the expression of VEGF in TME, which further delayed tumor growth in mice and prolonged disease-free survival in cancer patients." (PMID 29455663, 2018). "Furthermore, combining the oligoclonal antibody with a low dose of a third‐generation inhibitor of EGFR improved anti‐tumor efficacy, avoided recurrence, and durably cleared tumors in mice, features that may justify larger scale tests of 3×mAbs, either alone or in combinations, in clinical settings." (PMID 29212784, 2018). "EGFR was labelled MMP regulator and was found downregulated in lymph node metastasis vs primary tumours." (PMID 30231850, 2018). "Out of 712 patients, 515 (72%) had tumor tissue available for molecular testing; 37% (188/515) of tumors were analyzed using NGS methods, while 59% (306/515) were tested only for EGFR and ALK." (PMID 29854298, 2018). "Finally, we showed that tracking the dynamics of plasma EGFR mutations alone may not provide the most accurate estimate of tumour responses, as seen in the 14% of patients who progressed with decreasing levels of EGFR mutations in plasma." (PMID 29848757, 2018). "Many studies describe the growth-inhibitory functions of EGFR to be mediated by STAT1, which is an established tumor suppressor and mediator of apoptosis downstream of interferon signaling." (PMID 30250119, 2018). "Although tumour relapse was observed after 4 months, the combination uses of EGFR inhibitor, lapatinib with BGJ398 significantly deferred the tumour reversion." (PMID 29455663, 2018). "Together, the ensemble-averaged data and the mixture modeling indicated significant plasma membrane localization of EGFR and IGFR on human tumor EC-like cells." (PMID 30050899, 2018). "As expected, anti-EGFR has single agent activity against A431 in SCID mice, but the addition of human T cells greatly suppressed A431 tumor growth." (PMID 28585177, 2018). "To investigate the ability of 7A7 to target EGFR and modulate tumour growth in vivo, we used 7A7 to treat mice with established HPV38 or TC-1 tumours." (PMID 29552307, 2018). "In order to improve the outcomes of patients with mutant EGFR NSCLC, we need to define and target the basis of this variable initial response and the mechanisms by which tumor cells persist through the initial phase of therapy." (PMID 30097569, 2018). "Administration of the EGFR-TKI gefitinib and anticoagulant therapy resulted in a partial tumor response and recovery from both the coagulation abnormality and the severe neurological symptoms." (PMID 30034636, 2018). "EGFR participates in CCA progression, favoring the dedifferentiation and invasiveness of tumor cells and represents a bad prognostic factor." (PMID 30369925, 2018). "In contrast, there was a reverse correlation between MSI1/EGFR expression and tumor depth of invasion, in which MSI1 is involved in T3 depth of invasion, whereas the EGFR is involved in T2 depth of invasion." (PMID 30202417, 2018).
tumor (continued). "Epidermal Growth Factor Receptor (EGFR, HER1) belongs to a family of ErbB receptors that includes ErbB-1, ErbB-2, ErbB-3 and ErbB-4, and is critical for tumor development, metabolic and physiological processes." (PMID 30680072, 2018). "Several reports have suggested the cross talk between TGF‐β signaling and other pathways, including EGFR signaling during cancer progression, and this finding possibly explains why TGF‐β favors tumor progression in late stages." (PMID 29215776, 2018). "Overexpression of EGFR was observed specifically in 68% of the ESCC patients and it was significantly correlated with clinical stage, tumor invasion, and poor survival outcome." (PMID 29455652, 2018). "Alternative pathway activation involving EGFR, KRAS, KIT, ERBB, MET and IGF-1R are also responsible for ALK+ tumor crizotinib resistance." (PMID 29455659, 2018). "EGFR subjected to low concentrations (< 2 ng/ml) of EGF are internalized via CME and this is the physiologically relevant concentration in tumours." (PMID 30409180, 2018). "When a specific blocker for αVβ3 is used, reduced PANC-1 tumor mass in a mouse xenograft model, increased proapoptotic BcLx-s expression, reduced tumor hemoglobin content (a marker of angiogenesis), and decreased expression of epidermal growth factor receptor (EGFR) could be observed." (PMID 30013597, 2018). "The present study demonstrated that afatinib exerted greater anti-tumor effects on ESCC cell lines and PDXs than other-generation EGFR-TKIs or mAbs in vitro and in vivo." (PMID 30157900, 2018). "The combination of afatinib with paclitaxel significantly improved tumor response and PFS compared with paclitaxel alone in patients who had EGFR tyrosine kinase inhibitor (TKI)-resistant (including afatinib) disease." (PMID 30088048, 2018). "Both miR-3140 and si-EGFR reduced the expression of EGFR in NCI-H1975 cells, resulting in the suppression of in vitro tumor cell growth in NCI-H1975 cells." (PMID 29540837, 2018). "These two approaches have been already successfully applied to other nanobodies, such as those targeting VEGFR2 or EGFR, as well as to VIP derivatives to induce tumor cell death." (PMID 29674997, 2018). "Preventing this by means of a triple combination of mAbs to EGFR, HER2 and HER3 (hereinafter, 3×mAbs) robustly inhibited tumor growth." (PMID 29212784, 2018). "In the study of cell lines, IGF-1R leads to EGFR-TKI resistance by regulating the metabolism, proliferation and apoptosis of tumor cells and continuously activating the PI3K-AKT signaling pathway." (PMID 29455664, 2018). "All the 25 EGFR-positive lymph node metastases were clearly identified with the ICG-specific fluorescence signal, while the EGFR-negative tumor specimens produced a much weaker signal." (PMID 29856819, 2018). "The EGFR/extracellular signal-regulated kinase (ERK) pathway leads to tumour cell proliferation, survival and chemotherapy resistance, and it is induced by PTX, and inhibited by MicroRNA-7 (miR-7) by downregulating EGFR expression." (PMID 29966369, 2018). "In contrast, the median transcript ratios of the 19 adjacent non-tumor tissues were 0.2 copies HIF-1α mRNA per HPRT mRNA copy (ranging from 0–1.6; mean 0.3) and 0.06 copies EGFR mRNA per HPRT mRNA copy (range 0–0.3, mean 0.07)." (PMID 30513863, 2018). "Here, we analyzed scFv-Fc-scTRAIL molecules directed against EGFR, HER2, HER3, and EpCAM as well as an untargeted Fc-scTRAIL fusion protein for their potentials to induce cell death both in vitro and in a xenograft tumor model in vivo." (PMID 29541416, 2018). "In EGFR-overexpressed animal model, this nanoformulation-mediated PDT significantly suppressed tumor growth through the inhibition of cell proliferation." (PMID 29470420, 2018). "However, tumor burden alone was not sufficient to explain the higher T790M abundance in patients in the OF group compared to those in the CF and BF groups because T790M abundance is calculated from the ratio of T790M mutation to total EGFR copy number." (PMID 29789021, 2018).